ADAMTSL4 (ADAMTS like 4)
Diseases named in the same sentence as ADAMTSL4 in open-access papers (continued):
Sharing a sentence is not in itself a finding about the gene and the disease.
tumor (13 papers, 2011 to 2025). "ADAMTSL4 is one of the most widely studied members, is associated with aggressive tumor phenotypes, and participates in microfibril formation and function." (PMID 36761753, 2023). "Studies have shown that ADAMTSL4 is associated with immune-related processes in GBM and reflects the infiltration of complex immune cells and TME environment in tumor." (PMID 40224547, 2025). "The potential roles of PDZRN3 and ADAMTSL4 in regulating tumor immune microenvironment are worth exploring." (PMID 35087839, 2021). "Consistently, ADAMTSL4 showed a similar behaviour in our study, suggesting that it has an inverse interaction with tumour purity." (PMID 33869274, 2021). "Here, we uncovered the correlation between ADAMTSL4 and general changes of tumor microenvironment in pGBM." (PMID 30728876, 2019). "Investigation of the involved biological characteristics revealed the consistency of ADAMTSL4 with immune response, induced infiltration of immune cells, and tumor microenvironment." (PMID 30728876, 2019). "Thus, it is reasonable to identify ADAMTSL4 as a tumor suppressor gene for NPC preventing the tumor progression and metastasis, which is well consistent with its positive regulation apoptosis function." (PMID 28107202, 2017). "The present studies suggest for the first time that ADAMTSL4 could be a potential serum tumor marker for predicting the NPC metastasis." (PMID 28107202, 2017). "In addition, the ADAMTSL4 expression was shown with lower tumor purity in the CGGA database." (PMID 30728876, 2019). "The validation part demonstrated that ADAMTSL4, DOCK6, FAM111B, and SEMA6B were expressed at higher levels in the tumor tissue, whereas lower expression of MRPS10 and PSMB7 was observed." (PMID 36761753, 2023). "ADAMTSL4 and ANGPTL7 proteins were significantly overexpressed in adjacent non-tumour tissues compared with tumour tissues." (PMID 33869274, 2021). "Higher ADAMTSL4 expression implies worse prognosis of primary GBM (WHO grade IV) patients, correlated with more intensive immune response and complicated tumor microenvironment." (PMID 30728876, 2019). "Bioinformatic analyses revealed that ADAMTSL4 was significantly correlated to the immune-related processes in GBM (WHO grade IV), especially representing the infiltration of immune cells and complicated tumor microenvironment." (PMID 30728876, 2019). "All these findings showed that ADAMTSL4 could be an independent biomarker to predict poor prognosis in primary GBM (WHO grade IV) by revealing more complicated immune status and tumor microenvironment." (PMID 30728876, 2019). "It revealed that all these five targets (GSN, ADAMTSL4, CALR, PPIA and TXN) can be secreted by the NPC 6-10B and 5-8F cells, which provided an important basis for our following studies to identify the serum tumor biomarkers of NPC." (PMID 28107202, 2017). "The present data show for the first time that the ADAMTSL4 and TXN may be novel and potential biomarkers for predicting the NPC metastasis.Furthermore, the serum ADAMTSL4 could be a potential serum tumor biomarker for prognosis of NPC." (PMID 28107202, 2017). "The results indicated that ADAMTSL4 could effectively reflect the general changes of tumor microenvironment, but not linking to any specific immune cell activity." (PMID 30728876, 2019).
cancer (4 papers, 2018 to 2022). A tumor composed of atypical neoplastic, often pleomorphic cells that invade other tissues. "Chromosome 1 carries several amplified genes already reported in cancer such as ADAMTSL4, Histon2H gene family, MUC1 and TOMM20." (PMID 29844869, 2018).
cardiovascular disease (1 paper, 2024).
connective tissue disorder (1 paper, 2010). A disease involving the connective tissue. "Four members of the ADAMTS superfamily, ADAMTS10, ADAMTS17, ADAMTSL2 and ADAMTSL4 have been implicated in connective tissue disorders, including ADAMTSL2, the cause of GD." (PMID 20862248, 2010).
ADAMTSL4 also shares sentences with these, for which no sentence is quoted: craniosynostosis (3 papers); infection (2); myopia (2); nervous system diseases (2); acute lymphoblastic leukaemia (1); congenital cataracts (1); Coronary artery dissection (1); esophageal cancer (1); hepatocellular carcinoma (1); homocystinuria (1); hyperopia (1); liver disease (1); melanoma (1); osteoarthritis (1); osteoporosis (1); retinal detachment (1); schizophrenia (1); Traboulsi syndrome (1); Weill-Marchesani-like syndrome (1).